STAT3 (signal transducer and activator of transcription 3)
Diseases named in the same sentence as STAT3 in open-access papers (continued):
Sharing a sentence is not in itself a finding about the gene and the disease.
breast cancer (continued). "For example, PLK4-driven centrosome amplified breast tumor cells have been reported to be highly sensitive to inhibitors of the STAT3 (signal transducer and activator of transcription 3) protein, an emerging potential therapeutic target in breast cancer." (PMID 41092110, 2025). "For instance, resveratrol improves chemosensitivity in breast cancer by reversing macrophage polarization, lowering IL‐6 levels, and inhibiting STAT3 activation." (PMID 41394539, 2025). "STAT3 has indeed been identified as a key target in the occurrence, development, and drug resistance of breast cancer." (PMID 40076902, 2025). "Critically, BPA-exposed adipocytes show increased expression of inflammatory cytokines, IL-6, IL-1β, and TNFα, which are known to activate key oncogenic pathways in breast cancer cells, such as STAT3 and NF-κB." (PMID 40034592, 2025). "The molecular mechanism of IL-6 in breast cancer is likely context-dependent, involving interactions between the STAT3-dependent pathway and the growth-promoting MAPK/PI3K pathway." (PMID 41226910, 2025). "The IL-6/STAT3 signaling pathway has a key effect on breast cancer, enhancing cell proliferation, survival, and epithelial-mesenchymal transition, notably in triple-negative breast cancer (TNBC)." (PMID 40420174, 2025). "Leptin secreted from adipocytes activates JAK-STAT3 signaling pathway in breast cancer stem cells (BCSCs), which heightens FAO via STAT3 association with CPT2 promoter, contributing to tumor spheroid forming." (PMID 40290117, 2025). "It contributes to the growth and stemness of tumor cells in breast cancer through the signal transducer and activator of transcription 3 (STAT3) signaling pathway." (PMID 40863244, 2025). "The study confirmed that breast cancer-derived exosomes mediated macrophage polarization via the gp130/STAT3 pathway." (PMID 40103824, 2025). "Overexpression of CCL2 enhances stemness and macrophage polarization in breast cancer via STAT3 and Notch-1 signaling cascade, whereas silencing it increases tumor necrosis and autophagy, resulting in reduced CSC population and macrophage recruitment." (PMID 39858015, 2025). "For example, STAT3 inhibition in MDA-MB-231 TNBC breast cancer cells sensitized cells to doxorubicin treatment, resulting in increased cell death." (PMID 40507264, 2025). "Another report showed that IL-6 induces STAT3-mediated miR-21 activation, and functions as an epigenetic switch in breast cancer." (PMID 40843360, 2025). "The silk particle potential was analyzed using siRNA for silencing STAT3 expression in the HER2+ breast cancer model." (PMID 40584785, 2025). "Elevated IL-6 secretion from senescent cells and subsequent activation of STAT3 reinforce a pro-inflammatory microenvironment that promotes tumorigenic potential in breast cancer." (PMID 41148817, 2025). "It is known that STAT3-directed siRNA has been used to sensitise breast cancer cells to doxorubicin and neuroblastoma cells to cisplatin." (PMID 40729003, 2025). "For instance, PGRN upregulates PD-L1 expression and triggers M2 polarization via activation of STAT3, resulting in immunosuppressive PD-1/PD-L1 interaction in breast cancer." (PMID 39858015, 2025). "We identified 15,474 breast cancer-associated genes, emphasizing the HR+/HER2-subtype and the role of the tumor microenvironment in metastasis via STAT3 and p65 regulation." (PMID 40081286, 2025). "These comprehensive findings provide a sufficient theoretical basis for further experimental verification of the role of JAK2/STAT3 axis in the anti-breast cancer mechanism of RT." (PMID 40351419, 2025). "STAT3 can be activated in breast cancer by a number of cytokines and growth factors, including interleukin-6 (IL-6), OSM, IGF, FGF, and EGF." (PMID 40507264, 2025). "Further investigation showed that the release of exosomes containing miR-378a-3p and miR-378d is induced by activation of the EZH2/STAT3 axis in breast cancer." (PMID 39858015, 2025).
breast cancer (continued). "In breast cancer, tumor cells activate astrocytes via signal transducer and activator of STAT3 signaling, leading to the formation of tumor–astrocyte gap junctions, similarly observed in SCLC." (PMID 41429896, 2025). "Consistently, the immunofluorescent staining of breast cancer cells with SNRPE knockdown revealed significantly decreased level of STAT3." (PMID 40386046, 2025). "Data from 1,008 patients with breast cancer in The Cancer Genome Atlas were analyzed to evaluate the prognostic significance of STAT3 expression using Kaplan-Meier survival analysis and Cox regression models." (PMID 40636126, 2025). "In this study, we demonstrate that the ferroptosis inducer RSL3 triggers STAT3 ubiquitination and subsequent degradation, ultimately enhancing autophagy and apoptosis in PARPi-resistant breast cancer cells." (PMID 41463402, 2025). "In breast cancer patients with bone metastases, elevated IL-11 mRNA and increased expression of p38, p-c-Jun, and p-STAT3 have been observed, highlighting its predictive value for bone metastatic potential." (PMID 40909271, 2025). "The Western blot results showed that leptin-induced MTA1 upregulation was suppressed by all these inhibitors, confirming that leptin regulates MTA1 expression via the Ob-R/STAT3 signaling pathway in breast cancer cells." (PMID 40565190, 2025). "STAT3 also has been shown to bind to the gene encoding TNFRSF1A which can upregulate NF-kB signaling in TNBC, ultimately promoting breast cancer cell survival and proliferation." (PMID 40507264, 2025). "While both are involved in mammary gland development and can be activated in breast cancer, STAT5 tends to promote differentiation and survival, while STAT3 can be associated with proliferation and survival, but also apoptosis." (PMID 41301421, 2025). "Exosomes play a critical role in the tumor microenvironment by interacting with signaling pathways that facilitate breast cancer metastasis, particularly the STAT3 pathway." (PMID 40952540, 2025). "Tamoxifen impacts the binding of cyclin D1 with ER and STAT3 in cyclin D1-overexpressing breast cancer cells, abolishing cyclin D1-mediated inhibition of STAT3 and growth suppression, allowing STAT3 to exhibit anti-apoptotic activity." (PMID 40949156, 2025). "For example, the small-molecule STAT3 inhibitor napabucasin has been shown to attenuate the tamoxifen resistance of breast cancer cells by reducing the CSC properties." (PMID 40075607, 2025). "From a mechanistic perspective, in breast cancer tumors associated with obesity, CD8 + T cells bind to leptin and PD-1, resulting in diminished effector functions via STAT3 activation." (PMID 40069732, 2025). "By stimulating genes related to cell proliferation, apoptosis resistance, and metastasis, STAT3 is frequently active in malignancies such breast cancer, lung carcinoma, and melanoma, which accelerates the course of the disease." (PMID 41155227, 2025). "Unpublished data from our group show that OB EVs are enriched in palmitic acid and fatty acid binding protein 4 (FABP4), a molecule known to promote breast cancer progression through the IL-6/STAT3/ALDH1 pathway." (PMID 40485730, 2025). "RT-qPCR results of a cross-sectional study showed that JAK2 wasdecreased and STAT3 elevated gene expression level in breast cancer; there was also a positive correlationbetween JAK2 and STAT3 expression." (PMID 40092547, 2025). "Lactate activates the ERK/STAT3 signaling cascade, which promotes angiogenesis, migration, and cell proliferation in breast cancer by driving polarized macrophages to the M2 type." (PMID 40295451, 2025). "This study uniquely explores Melittin’s interactions with JAK2, JAK3, and STAT3, which are crucial components of breast cancer signaling pathways." (PMID 40243485, 2025).
breast cancer (continued). "It has been demonstrated that STAT3 plays critical roles in migration, proliferation, epithelial-to-mesenchymal transition (EMT), and chemoresistance, making the STAT3 signaling pathway a desirable target for breast cancer." (PMID 40507264, 2025). "We discovered that chalcone-9 inhibited the activation of the JAK-STAT signaling pathway, decreased the mRNA expression of STAT1 and STAT3 target genes, and impaired cancer cell functions in breast cancer cells." (PMID 40199813, 2025). "Evidence indicates that excessive activation of STAT3 plays a broad role in the development of many cancer types, including brain tumors, lung cancer, breast cancer, melanoma, and metastasis formation." (PMID 40869314, 2025). "In a previous study, it was shown that CDYL2 recruits G9a and EZH2 to epigenetically repress miR124, which promotes NF-κB and STAT3 activation and negatively impacts the prognosis of breast cancer." (PMID 40843360, 2025). "For example, in breast cancer, STAT3 is frequently activated by interleukin-6 (IL-6) through the Janus kinase (JAK) pathway, promoting an inflammatory microenvironment that fosters tumor growth." (PMID 40075607, 2025). "Persistent activation and overexpression of STAT3 have been consistently observed in various cancers, including breast cancer, and are strongly correlated with poor clinical prognosis." (PMID 40949156, 2025). "For example, the oncogenic lncRNA TINCR brings DNMT1 to the promoter of miR-503-5p, resulting in hypermethylation and decreased expression, which in turn leads to increased STAT3 levels and promotes breast cancer progression." (PMID 40843360, 2025). "Prior studies on similar analogs, including compounds #7 and #11, showed clear activity against AR/AR-SVs in PCa, Wnt-ß-catenin, mTORC1, and STAT3 in ovarian cancer and NF-κB in breast cancer." (PMID 40805231, 2025). "The development of STAT3 inhibitors and degraders is a new direction for the treatment of breast cancer." (PMID 40076902, 2025). "For example, IL-6 secreted by MSCs in colorectal cancer can activate JAK2/STAT3 signaling, promoting cancer progression, whereas MSC-conditioned media has been reported to inhibit STAT3 levels in breast cancer, suggesting potential anti-tumor effects." (PMID 40444089, 2025). "When MDA-MB-468 TNBC breast cancer cells, which have constitutively active STAT3, were forced to express constitutively active STAT5, the genotypic profile of these cells matched the genotypic profile of tumors expressing both STAT3 and STAT5." (PMID 40507264, 2025). "STAT3 is constitutively activated in all breast cancer subtypes but mainly in triple-negative cancer." (PMID 40841364, 2025). "Tumor-derived lactate activates the ERK/STAT3 signaling pathway, which leads to M2 macrophage polarization in breast cancer." (PMID 39858015, 2025). "While clinical translation requires further validation, our findings demonstrate radiomics’ potential as a non-invasive tool for STAT3 expression profiling and prognostic assessment in breast cancer, representing a significant step toward precision oncology." (PMID 40636126, 2025). "Another study employed HPMA‐based copolymers containing Dox and the STAT3 inhibitor cucurbitacin D for gradual drug release, demonstrating effectiveness in breast cancer treatment." (PMID 40166646, 2025). "We previously demonstrated that TTI-101 targets STAT1, in addition to STAT3, in human radioresistant head and neck squamous cell carcinoma cell lines and that it also targets STAT5 in a mouse model of increased breast cancer risk caused by pregnancy." (PMID 41226842, 2025). "High fibronectin expression in breast cancer is associated with shorter patient survival and EMT promotion via the STAT3 pathway." (PMID 40230452, 2025). "Llanes-Fernándeza et al122 previously reported that 85% (23 out of 27) of the breast cancer tissue studied from elderly individuals showed significant IL-10 expression (STAT3 in cancer cells)." (PMID 40584290, 2025).
breast cancer (continued). "The inhibition of the JAK/STAT3 axis blocks breast cancer stem cell self‐renewal and fatty acid β‐oxidation, leading to resensitization to chemotherapy." (PMID 40415238, 2025). "In conclusion, our study uncovers a previously unrecognized mechanism by which RSL3 promotes STAT3 ubiquitination and degradation, leading to autophagy and apoptosis in PARPi-resistant breast cancer cells." (PMID 41463402, 2025). "Our previous research confirmed the molecular mechanism driving tamoxifen-resistant breast cancer cells, revealing the crucial role of STAT3 signaling in tamoxifen resistance." (PMID 40199813, 2025). "For example, CYP3A4 has been reported to increase the growth of breast cancer by facilitating the nuclear translocation of p-STAT3 partially through the synthesis of (±)-14,15-epoxyeicosatrienoic acid (EET)." (PMID 39754188, 2025). "Several other studies have supported the observation that increased STAT3 activity corresponds with poorer breast cancer prognosis, especially in TNBC." (PMID 40075607, 2025). "Through kinase array experiments, we found that SUSD2 expression was modulated downstream of STAT3-dependent signaling in breast cancer cells overexpressing HER2." (PMID 39791720, 2024). "Alantolactone was confirmed to possess STAT3 inhibition property and great potential for pancreatic cancer, breast cancer treatment." (PMID 38822350, 2024). "ROS generation and interleukin (IL)-6-triggered STAT3 activation regulates MDSC expansion in breast cancer." (PMID 38625901, 2024). "This IL-6 signaling pathway positively interacts with the Stat3 pathway, resulting in tumor promotion and an increase in breast cancer stem cells, mainly in the triple-negative subtype." (PMID 38813102, 2024). "The JAK2/STAT3 pathway plays an important role in the deterioration of breast cancer, including proliferation and metastasis." (PMID 38686052, 2024). "Enhanced levels of tyrosine-phosphorylated signal transducer and activator of transcription 3 (p-STAT3) are found constitutively in about half of human breast cancers." (PMID 39064812, 2024). "IL-6/JAK/STAT3 pathway leads to EMT activation not only in breast cancer but also in cervical carcinoma." (PMID 38892394, 2024). "In conclusion, our findings suggest that FGF21 promotes the anti-apoptotic ability of breast cancer cells via Akt and STAT3 pathways." (PMID 38238320, 2024). "For example, FOSL1 has been reported to upregulate the expression of IL-6 in breast cancer cells, which can promote tumor growth and invasion by activating the STAT3 signaling pathway." (PMID 38791400, 2024). "In many human cancers, including breast cancer, STAT3 and STAT5 are persistently phosphorylated and overactivated." (PMID 39057095, 2024). "It has been reported that the STAT3/HIF-1α pathway is closely associated with the progression of various tumors, including prostate cancer, hepatocarcinoma, breast cancer, and ovarian cancer." (PMID 38990440, 2024). "This pSTAT3/p27pT157-activated gene expression profile identified in human breast cancers was strongly overexpressed in 231DD and 1833 compared to 231 and 1833shp27, further validating the relevance of our p27/STAT3 driven gene expression in human disease." (PMID 38886396, 2024). "It was shown that the constitutive activation of STAT3 leads to the development of head and neck tumors, breast cancer, non-small-cell lung cancer, colorectal cancer, and hematological tumors." (PMID 39136000, 2024). "Conforming to this correlation, the addition of acetyl-CoA partially counteracted the impacts of suppressing STAT3 on the growth and viability of breast cancer stem cells (BCSCs)." (PMID 38933330, 2024). "STAT3 decoy ODNs combined with irradiation and methotrexate show a better efficacy than singe irradiation or methotrexate treatment in metastatic breast cancer cell line." (PMID 38245798, 2024).
breast cancer (continued). "Research findings indicate that Plerixafor is capable of inhibiting the activation of the STAT3 signaling pathway, thereby suppressing the development of breast cancer and prostate cancer." (PMID 38920657, 2024). "STAT3 is a transcription factor that affects breast cancer progression and chemoresistance by regulating several oncogenes and participates in the leptin/Ob-R signaling pathway." (PMID 38791252, 2024). "IL-11 through STAT3 activation stimulates osteoblast activity, which is dominant in the metastasis of breast cancer cells to the bone." (PMID 38892394, 2024). "The AM-18002 and IR combination synergistically induced cancer cell death, and AM-18002 acted as a potent anticancer agent by increasing ROS generation and blocking MDSC-mediated STAT3 activation in breast cancer cells." (PMID 38625901, 2024). "Lactic acid bacteria have been found to reduce Stat3 expression and secrete IL-6, thereby inhibiting breast cancer stem cells, suggesting their potential in breast cancer treatment and prevention." (PMID 39360320, 2024). "STAT3 inhibition by the nutrient silibinin has been shown to be able to suppress breast cancer cell growth in preclinical models and induce responses in patients with BM from NSCLC." (PMID 38893253, 2024). "Research findings indicate that the CXCL12 and STAT3 proteins are significantly upregulated in various malignancies, including breast cancer, lung cancer, hepatocellular carcinoma, esophageal cancer, bladder cancer, and leukemia." (PMID 38920657, 2024). "Sodium propionate demonstrates anticancer effects by modulating the JAK2/STAT3/ROS/p38 MAPK signaling pathway in breast cancer xenografts in mice." (PMID 39717276, 2024). "The constitutive expression of Twist in breast cancer cells can result from inappropriate production of IL-6 and STAT3 phosphorylation." (PMID 38519574, 2024). "PTPN12 repression facilitates STAT3 activation by Pyk2 and ES-TF expression, and the observed p27-driven increases in mammospheres and in tumor formation by breast cancer initiating cells in vivo." (PMID 38886396, 2024). "In breast cancer, the miR-17-5p/STAT3/H19 axis was found to regulate the expression of STAT3, thereby affecting the proliferation and metastasis of cancer cells." (PMID 39830506, 2024). "Specific to breast cancer, STAT3 promotes tumor proliferation and is active in invasive breast cancer biopsies samples but not in benign breast tumors." (PMID 38339245, 2024). "Our findings suggest the clinical significance of SUSD2 as a biomarker for EGFR+ HER2+ breast cancer and highlight the use of STAT3-specific inhibitors for treating EGFR+ HER2+ breast cancer expressing SUSD2." (PMID 39791720, 2024). "By analyzing human breast cancer specimens, we observed a substantial increase in the expression of STAT3 protein in invasive breast carcinoma and tumor that had metastasized to lymph nodes." (PMID 38691208, 2024). "The mechanism of metochalcone against breast cancer depended on the induction of SASP via deactivation of the JAK2/STAT3 pathway, highlighting the potential of chalcone in senescence-inducing therapy against carcinomas." (PMID 38686052, 2024). "Leptin plays a vital role in the development and progression of breast cancer by activating STAT3 signaling." (PMID 38791252, 2024). "One of the most common mechanisms of traditional Chinese medicine and natural products against breast cancer is modulation of the JAK2/STAT3 pathway." (PMID 38686052, 2024). "These authors further demonstrated that FA2H suppresses cancer stemness in breast cancer cells by inhibiting the STAT3/IL6 axis and NFkB signalling." (PMID 39233332, 2024). "CircNOLC1 as another ceRNA by sponging miR-365a-3p increased STAT3 expression and contributed to the CSCs characteristics of breast cancer." (PMID 39170516, 2024). "IL-10, produced by TAMs, enhanced paclitaxel resistance via activation of STAT3 and upregulation of Bcl-2 in breast cancer cells." (PMID 38794298, 2024).